BFAR (bifunctional apoptosis regulator)
Description:
Membrane-bound E3 ubiquitin ligase that plays a role in several processes including apoptosis regulation or reticulum endoplasmic stress. Has anti-apoptotic activity, both for apoptosis triggered via death-receptors and via mitochondrial factors. Contributes to the dynamic control of IRE1/ERN1 signaling during ER stress by inducing BAX inhibitor 1/TMBIM6 proteasomal degradation. Promotes the activation of TGF-beta signaling by mediating the 'Lys-63'-linked ubiquitination of TGFBR1 which is critical to activate the pathway. Together with NGFR, negatively regulates NF-kappa-B and JNK-related signaling pathways. Promotes the proteasome-mediated degradation of PNPLA3, a protein involveld in lipid metabolism.
Synonyms: BAR; RNF47
Tractability: Antibody: UniProt predicts a signal peptide or a membrane-spanning region. PROTAC: UniProt records ubiquitination sites on it; ubiquitination databases record sites on it; its protein half-life has been measured.
Gene: Protein-coding gene on chromosome 16 (14,632,830 to 14,669,237, forward strand). Ensembl gene ENSG00000103429.
Subcellular location: Endoplasmic reticulum membrane
Gene Ontology:
Molecular function: caspase binding; protein binding; protein-macromolecule adaptor activity; ubiquitin protein ligase activity
Biological process: negative regulation of apoptotic process; negative regulation of IRE1-mediated unfolded protein response; proteasome-mediated ubiquitin-dependent protein catabolic process; protein autoubiquitination; protein K48-linked ubiquitination; protein K63-linked ubiquitination; protein polyubiquitination; ubiquitin-dependent protein catabolic process
Cellular component: endoplasmic reticulum; endoplasmic reticulum membrane; membrane; plasma membrane
Genetic constraint (gnomAD): Loss-of-function variants: 52 observed, 56.53 expected, observed/expected ratio (o/e) 0.92, 90% interval 0.74 to 1.16. The upper end of that interval is the gene's LOEUF score, 1.16, which puts it in group 5 of 6, group 1 being the genes least tolerant of losing a copy. Missense variants: 571 observed, 559.17 expected, observed/expected ratio (o/e) 1.02, 90% interval 0.95 to 1.09. Synonymous variants: 215 observed, 212.28 expected, observed/expected ratio (o/e) 1.01, 90% interval 0.9 to 1.13.
Homologues: Orthologues: chimpanzee BFAR (99% identical), macaque BFAR (98% identical), dog BFAR (93% identical), guinea pig BFAR (92% identical), pig BFAR (90% identical), rat Bfar (90% identical), mouse Bfar (90% identical), rabbit BFAR (89% identical), tropical clawed frog bfar (76% identical).
Diseases named in the same sentence as BFAR in open-access papers:
BFAR is named in the same sentence as 4 diseases in open-access papers, as found by Europe PMC text mining. Sharing a sentence is not in itself a finding about the gene and the disease. The quoted sentences say what the papers report.
melanoma (1 paper, 2024). A malignant, usually aggressive tumor composed of atypical, neoplastic melanocytes. "Hence, prospective studies should aim to examine SRC-3 and BFAR as potential new targets for melanoma treatment through their inhibition by bufalin." (PMID 38178183, 2024).
Sepsis (1 paper, 2025). Sepsis is defined as life-threatening organ dysfunction caused by a dysregulated host response to infection. "In the Severe vs. Control group, the genes associated with ER stress, including CLU (p = 0.01), BCL2L1 (p = 0.015), USP14 (p = 0.046), BFAR (p = 0.004), and OPA1 (p = 0.012), demonstrated a significant positive correlation with sepsis score." (PMID 40867920, 2025). "This study presents findings on several genes linked to ER stress, including CLU, BCL2L1, USP14, BFAR, and OPA1, which showed a positive correlation with sepsis score and a negative correlation with the combined activities of antioxidant enzymes." (PMID 40867920, 2025).
tumor (3 papers, 2019 to 2023). "BFAR has been recognized as an inhibitor of apoptosis with an alary helix DNA-binding structure and is tightly linked with tumour progression." (PMID 38106991, 2023). "The profiling data showed that 7 apoptosis-related genes were concordantly > twofold downregulated in recurrent tumor samples compared with the expression in paired primary tumor samples, including AKT1, BAG4, BCL2A1, BFAR, CARD6, CASP8 and TNFRSF21." (PMID 34488754, 2021). "Notably for FAT4, BFAR, CRB2, and PEX14, we did not identify somatic mutations in the wild-type allele of these genes in the cases carrying germline mutations, suggesting that if they are contributing to tumor formation, they most likely do not function as classical tumor suppressors." (PMID 31101826, 2019).
BFAR also shares sentences with these, for which no sentence is quoted: glioma (2 papers).